SOX5 (SRY-box transcription factor 5)
Diseases named in the same sentence as SOX5 in open-access papers (continued):
Sharing a sentence is not in itself a finding about the gene and the disease.
SOX5 also shares sentences with these, for which no sentence is quoted: autism (5 papers); depression (3); atrial fibrillation (2); cervical cancer (2); cognition disorder (2); endometrial carcinoma (2); lymphoma (2); meningioma (2); testicular seminoma (2); acute myeloid leukemia (1); Alpha-thalassemia (1); autism spectrum disorder (1); Autoimmunity (1); bone resorptive diseases (1); brain disease (1); Brugada syndrome (1); campomelic dysplasia (1); cardiomyopathy (1); coloboma (1); colon cancer (1); diabetes (1); dilated cardiomyopathy (1); endocrine tumor (1); Ewing sarcoma (1); experimental autoimmune encephalomyelitis (1); fibromyalgia (1); fragile X syndrome (1); genetic disease (1); glioblastoma (1); hereditary spastic paraplegia (1).
A further 24 diseases each share a sentence with SOX5 in 1 paper.